WNT5A (Wnt family member 5A)
Diseases named in the same sentence as WNT5A in open-access papers (continued):
Sharing a sentence is not in itself a finding about the gene and the disease.
cancer (continued). "However, because some cancer cells have been noted to express Wnt5a, it is conceivable Wnt5a also might serve as an autocrine that can enhance the growth of turmors that co-express ROR1." (PMID 22403610, 2012). "However, the roles of Wnt5a/PCP signaling are poorly defined in cancer cells." (PMID 22655072, 2012). "It cannot be excluded that Wnt5a might play various roles in different types of cancer." (PMID 23342259, 2012). "Next, we evaluated if Wnt5a protein expression in cancer tissues analyzed after radical prostatectomy for localized PCa could predict clinical outcome as measured by time to biochemical recurrence (BCR), using PSA >0.2 ng/mL in blood samples with a confirmatory value as a surrogate marker." (PMID 22039506, 2011). "Hence, the presence or absence of these receptors may go some way to explain the conflicting role of Wnt-5a in different cancers." (PMID 19603030, 2009). "Therefore, it can be concluded that overexpression of Wnt-5a could have an oncogenic effect by stimulating cancer cell invasion." (PMID 19603030, 2009). "Previous literature suggests that SFRP5 inhibits WNT5A, a β-catenin-independent WNT protein that plays a critical role in regulating cell signaling pathways involved in development and cancer progression." (PMID 40301374, 2025). "The exosome-free serum WNT5A yielded the highest AUC value:0.9702, [CI]: 0.9099 to 1.000) comparing NSCLC patients with the HC group, separating cancer patients from healthy donors." (PMID 40223089, 2025). "The identified upregulation here of both Wnt5a and its co-receptor ROR2 is particularly intriguing due to their dual and often contradictory roles in cancer." (PMID 41007281, 2025). "Similar to the heterozygous CNV, including the percentage of homozygous amplification and deletion of the WNT5A gene in STAD and LUSC cancer types." (PMID 39176352, 2024). "Alternatively, the non‐canonical Wnt ligand, Wnt5a, is overexpressed in CRC and promotes cancer cell epithelial‐mesenchymal transition, facilitating metastasis." (PMID 38872420, 2024). "Cirmtuzumab, which targets the interaction between ROR1 and Wnt signaling, inhibits Wnt5a-mediated signaling by binding to ROR1, reducing cancer cell proliferation and survival." (PMID 39518123, 2024). "ROR1 can serve as a surface receptor for Wnt5a, which can induce ROR1 signaling, leading to activation of ERK1/2, NF-κB, and NRF2, and enhance cancer stemness." (PMID 39062146, 2024). "Wnt5a has been reported to induce EMT and cancer stem cells in OC via the TGF-β1/Smad2/3 and Hippo-YAP1/TAZ-TEAD pathways." (PMID 38191909, 2024). "The presence of WNT5A+ inflammatory fibroblasts was confirmed by the overlapping signals from the WNT5A, GREM1, and PDGFRA RNA probes in the desmoplastic stroma of cancer tissues." (PMID 38744958, 2024). "In conclusion, CAFs regulate the symmetric division of OCSCs as well as the dedifferentiation of bulk cancer cells to OCSCs through secretion of Wnt5a, which acts via its co-receptor ROR2, on neighboring cancer cells, phosphorylating PKC and CREB1." (PMID 38191909, 2024). "It has been shown that upregulation of WNT signaling via WNT5A through ROR1 and ROR2 can induce metabolic reprogramming and immune dysregulation in TME, which promotes cancer progression in various malignancies." (PMID 38558536, 2024). "WNT5A expression levels in LUSC and STAD were considerably higher than in standard samples across age, gender, race, and cancer stage." (PMID 39176352, 2024). "Our results showed that patients with high WNT5A levels and low DCLK1 levels in their cancer tissue (Group 1) had a somewhat better prognosis than those grouped based only on low DCLK1 expression." (PMID 37998393, 2023). "While the functions of singular WNTs, such as WNT5A and WNT3, have been extensively described in cancer, other family members still need to be characterized in detail." (PMID 36982422, 2023).
cancer (continued). "Cancer stem cell markers were also examined, which showed an upregulation in ALDH1A3, CD44, and WNT5A in amoeboid cells, and increased SOX2 and BMI1 in escaping cells." (PMID 37575281, 2023). "One significant feature of these phenotype cancer cells was their high expression of mesenchymal markers, such as CDH2, S100A4, MMP2, WNT5A, and ZEB1." (PMID 36553542, 2022). "Our data annotated 17 WNTs and found that WNT2B, WNT10A, WNT5A and WNT7B showed a similar cancer-positive pattern, and WNT7B was the most significant one." (PMID 35850748, 2022). "While positive staining for WNT7B was observed obviously in the cytoplasm of the majority of malignant tissues, WNT5A, FZD7 and GPC1 signals were presented on both the cytoplasm and membrane of cancer cells." (PMID 35850748, 2022). "WNT ligands also changed expression levels in cancers, e.g. WNT3A, WNT5A and WNT7B were upregulated in cholangiocarcinoma." (PMID 35850748, 2022). "Notwithstanding, gene expression data showed that WNT5A and YAP1 expression is moderately-to-strongly correlated in several cancer types." (PMID 33643710, 2021). "TRIM8 overexpression downregulated the protein expressions of Wnt5a, β-Catenin, c-Myc and Cyclin D1, and upregulated the protein expression of active Caspase-3 in LV-TRIM8 cancers." (PMID 33858426, 2021). "Wnt5a is upregulated in GBM and has been shown to drive proliferation and invasion in cancer stem cell (CSC) populations." (PMID 34957471, 2021). "In contrast, regions more H3K9ac-enriched in HeLa contained genes involved in cell–cell adherens junction (FE 2.0, P = 9.4 × 10–20) and pathways in cancer (FE 1.5, P = 9.9 × 10–8), including oncogenes such as ERBB2, WNT5A and BRAF." (PMID 33542322, 2021). "Analysis of gene expression data using TIMER 2.0 shows a moderate-to-strong correlation between WNT5A and YAP1 in several cancer types." (PMID 33643710, 2021). "Upon arriving in the bones, cancer cells migrate and take on stem-like or tumorigenic properties, as aided through Wnt or β-catenin signaling involving CHD11, CD24, and Wnt5A." (PMID 34685470, 2021). "More importantly, this report showed that, in histological samples, WNT5A had higher expression in fibroblasts (which were identified by α-SMA staining), compared to cancer cells." (PMID 32195251, 2020). "Together, our findings demonstrate that Wnt5a is crucial for TAM-mediated migration and invasion of cancer cells." (PMID 32228612, 2020). "Such being the case, Wnt5A, CTNNB1P1, SMAD4, and TCF4 was expressed primarily in the para-cancer tissues but were reduced to varying degrees in cancer tissues." (PMID 32273945, 2020). "We also found significant positive correlations between cancer‐related cytokine TNF‐α and (a) bcl‐2 (r > 0.1, P < 0.0001); (b) ΔNp63, c‐REL (r > 0.97, P < 0.0003); (c) WNT5A (r > 0.88, P < 0.01)." (PMID 31173474, 2019). "A comparison of genome-wide methylation profiles of NHK and cSCC cell lines revealed a statistically significant difference in methylation in 361 unique genes (adjusted p-value ≤ 0.01), including known cancer drivers (MAP2K2, WNT5A, COL4A1, BMP2 and FGF7)." (PMID 31336867, 2019). "A key ligand of this protein family is the Wingless-type MMTV integration site family member 5A (WNT5A), which has an important regulatory role on different cell functions and also in many cancers." (PMID 29930766, 2018). "We used an in vivo orthotopic xenograft mouse model with metastatic luciferase-labeled WNT5A-low DU145 cells and metastatic luciferase-labeled WNT5A-high PC3prostate cancer cells." (PMID 28886116, 2017). "Together, these findings confirmed that WNT5A promoted the motility and metastatic ability of NPC cells, which are typical characteristics of cancer stem cells." (PMID 25823923, 2015). "WNT5A and LGR4 regulate cell polarity, proliferation, survival and aberrant regulation often leads to pathological conditions including cancer." (PMID 26474308, 2015).
cancer (continued). "Taken together, Wnt5A-controlled PKA/β-catenin signaling regulate upregulation of ABCB1, cyclin D1, c-Myc and VEGF in MDR cancer cells for increased survival advantage under chemotherapeutic treatment." (PMID 25401518, 2014). "The production of Wnt5a protein in MCF-7 cells was accompanied by an increased ability of discoidin domain receptor 1 (DDR1) phosphorylation and by the improvement of the cancer cell phenotype." (PMID 24944588, 2014). "As reported by others, WNT5A, LBH, WISP1 and TCF4 were expressed at lower levels in ER+ cell lines compared to ER-ve cancer but also compared to immortalised normal breast cell lines, perhaps reflecting their ER-ve status." (PMID 23861811, 2013). "A similar trend was observed when Wnt5a and VEGF were compared; 65% (219/339) of the cancer cores exhibited strong staining for both Wnt5a and VEGF." (PMID 22039506, 2011). "Scoring data from Wnt5a, AR, VEGF and Ki-67 immunostained cores from benign and cancer tissues in duplicates mounted in a TMA." (PMID 22039506, 2011). "Addition of recombinant Wnt5a (rWnt5a) decreased the invasive behavior of both 22Rv1 and DU145 cancer cells." (PMID 22039506, 2011). "Furthermore, the Wnt5A gene was upregulated in a bronchial epithelial cell line in response to PM2.5 exposure and contributes to cancer progression and metastasis by regulating cell migration, polarity, and cytoskeletal dynamics." (PMID 41545904, 2026). "The structural versatility of FZD receptors, particularly FZD3, FZD5, and FZD6, enables their interaction with non-canonical Wnt ligands such as Wnt5a and Wnt11, which are often overexpressed in cancers, including breast, colorectal, and melanoma." (PMID 40376615, 2025). "The results supported the theory that Wnt5a functions as a cancer inhibitor in cells lacking the ability to synthesize hypotaurine." (PMID 40373156, 2025). "In our cohort, Wnt5a was expressed in 46.7% of SBA cases, primarily in cancer cells." (PMID 41008809, 2025). "Activation of RhoA by Wnt5a serves as a survival stimulus in cancer cells during non-adherent conditions due to evasion of anoikis." (PMID 37804416, 2024). "WNT Family Member 5A (WNT5A), a ligand that activates the noncanonical branch of the Wnt pathway, promotes cancer cell invasion and migration." (PMID 38240752, 2024). "Moreover, GEPIA databases were used to assess confirmation of the prognostic significance of WNT5A genes in OS for LUSC and STAD cancer types." (PMID 39176352, 2024). "Moreover, the heterozygous CNV, including heterozygous amplification and deletion of the WNT5A gene in LUSC and STAD cancer types." (PMID 39176352, 2024). "Encouraging findings on its efficacy in impairing metastasis formation in patients with cancers with low or absent WNT5A expression recently led to the patent application US20210008149 for Foxy-5 involvement in cancer relapse treatment and prevention." (PMID 39065798, 2024). "Furthermore, we included two cancers (LUSC and STAD) decided upon by the three databases (UALCAN, TIMER, and GEPIA) regarding WNT5A expression for further investigation." (PMID 39176352, 2024). "We have reported that MSC engulfment induces persistent gene expression changes in MDA-MB-231 cells with significant upregulation of WNT5A by hybrid cancer cells compared with nonengulfing counterparts." (PMID 37607007, 2023). "Similarly, in the context of cancer, PKA has been shown to phosphorylate DARPP-32 at Thr-34 in response to Wnt-5a-mediated stimulation of cAMP39." (PMID 36966223, 2023). "Based on results coming from other cancers, EBV might induce epigenetic reprogramming of LEF1 and Wnt5a." (PMID 37512809, 2023). "Although WNT5A functions in RCC cells have not yet been clearly revealed, WNT5A signaling is crucial for regulating the proliferation and invasion of many other cancer cells." (PMID 37173306, 2023).
cancer (continued). "They observed that in the ROR1+MCF7 cells, Wnt5a stimulated the ROR1-dependent cortactin phosphorylation which recruited ARHGEF1 (Rho guanine nucleotide exchange factor 1) to activate RhoA and promote cancer cell migration." (PMID 36873868, 2023). "However, patients with low WNT5A levels and high DCLK1 levels in their cancer tissue (Group 4) had a significantly worse prognosis than those grouped based only on high DCLK1 expression." (PMID 37998393, 2023). "Wnt family member 5A (WNT5A), an important Wnt protein family member, can strongly activate the Wnt signaling pathway by binding to the FZD4-LPR5 complex receptor and then accumulating β-Catenin, which contributes to poor outcomes in cancer patients." (PMID 37173306, 2023). "In contrast, sevoflurane, a volatile anesthetic frequently used in surgery, could inhibit the proliferation and invasion, and induce cancer cell apoptosis of LUAD and SCLC cells by blocking the lncRNA PCAT6/miR-326/WNT5a/β-catenin pathway." (PMID 37486552, 2023). "Enhanced expression of Ror1 and/or Ror2 in cancer cells can promote their proliferation, migration, invasion, survival or chemoresistance through activation of Rho-family GTPases, c-Src, MAP kinases or Akt in Wnt5a-dependent and/or -independent manners." (PMID 35493090, 2022). "In our data, GLRX was considered to regulate the cancer stem cell phenotype via non-canonical Wnt signaling pathways associated with RhoA and ABCG2 via Wnt5a and Wnt7b." (PMID 34794402, 2021). "Wnt5a is usually regarded as a prototypical non-canonical Wnt ligand, and its expression has been related to cancer progression." (PMID 33643710, 2021). "In particular, altered expression of WNT5A and WNT11, which predominantly activate non-canonical Wnt pathways, has been linked to metastasis in various cancers." (PMID 34298659, 2021). "Obviously, the notion of WNT5A as the sole ligand for human ROR2 no longer holds true which opens novel insights in the regulation of non-canonical WNT signaling in cancer." (PMID 34911552, 2021). "Furthermore, to validate the prognostic role of the Wnt5a-ROR signaling pathway in GC, a pan-cancer RNA-Seq option from the KM plotter was used." (PMID 34319035, 2021). "Moreover, Wnt5a and YAP expression are significantly correlated in specific cancer types, suggesting that the crosstalk between YAP/TAZ and the Wnt pathway is more intricate than previously thought." (PMID 33643710, 2021). "Although canonical Wnt signal generally acts by modulating the self-renewal activity of cancer stem cells, the effects of non-canonical Wnt5a on tumorigenesis are relatively diverse depending on cancer types and stages." (PMID 33972671, 2021). "High expression of WNT5A in this cancer is a negative overall survival and positive metastasis formation factor." (PMID 34702444, 2021). "Wnt5a is one of the potent signaling molecules that initiates responses involved in cancer through activation of both canonical and noncanonical signaling cascades." (PMID 34603445, 2021). "Taken together, these data indicate that Wnt5a might be a new functional TAM marker, providing a novel insight into targeting Wnt5a in cancer therapy." (PMID 32140070, 2020). "Consistently, Wnt5a knockdown reduced CCL2 expression in TAMs and their cancer-promoting activity." (PMID 33080952, 2020). "But again, the existence of a Wnt5a-NF-κB connection has not been conclusively demonstrated in cancer cells." (PMID 31510045, 2019). "Wnt5a is a non-canonical Wnt-protein involved in developmental processes, inflammation, and certain forms of cancer." (PMID 31098409, 2019). "In line with the notion above, regulation of inflammation has not been considered as a frequent and important effect of Wnt5a in cancer." (PMID 31510045, 2019). "ALCAM was expressed in 69% of Wnt5a-positive but only 27% of Wnt5a-negative cancers (κ = 0.444; P < 0.001)." (PMID 29765514, 2018).
cancer (continued). "Wnt5a is a key factor of the non-canonical Wnt pathway and plays diverse roles in different types of cancer." (PMID 28859077, 2017). "Wnt5a is a key factor in the non-canonical Wnt pathway, and it plays diverse roles in different types of cancers." (PMID 28859077, 2017). "We hypothesized that the effect of C10 on viability/growth and migration of these cancers was related to its suppressive effect on TLR3 signaling which led to the inhibition of TLR-mediated STAT3 and Wnt5a signaling." (PMID 29371911, 2017). "Moreover, Wnt5a releases intracellular calcium, activating calcium-dependent proteins such as protein kinase C (PKC), which is essential for invasion in cancer cells." (PMID 28320399, 2017). "In another scenario, reduced expression of WNT-5A antagonists such as Klotho might contribute to increased availability and signaling of WNT-5A in cancer cells." (PMID 26514730, 2016). "WNT5A, a secreted signaling protein involved in canonical and non-canonical WNT signaling, and FZD7, a receptor for WNT5A and other WNT proteins, are both overexpressed in numerous cancers where they contribute to the EMT phenotype." (PMID 27574697, 2016). "Of particular importance to this study is the finding that the WNT5A gene is silenced by epigenetic mechanisms, primarily DNA methylation but also histone modifications, in cancers in which the gene is not expressed." (PMID 26978652, 2016). "We then found that WNT5A promoted epithelial-mesenchymal transition (EMT) in NPC cells, induced the accumulation of CD24-CD44+ cells and side population, which are believed to be cancer stem cell characteristics." (PMID 25823923, 2015). "We first analyzed the cellular phenotypes that are modulated by Wnt5a and non-canonical Wnt signaling during different stages of cancer progression." (PMID 26126266, 2015). "Next, we investigated how non-canonical Wnt signaling via the Wnt5a/FZDR-Daple-Gαi axis impacts cancer cell behavior." (PMID 26126266, 2015). "Wnt5a, a ligand for activating the non-canonical Wnt signaling pathway, is commonly associated with Epithelial-to-mesenchymal transition (EMT) in cancer cell metastasis." (PMID 25779663, 2015). "Moreover, genes in the WNT, SHH, and BMP pathways such as WNT5A, FZD7, and FZD5, SHH, SMO, and GLI2 as well as BMP4 were likewise among the upregulated genes and were included in pathway of cancer gene set." (PMID 26998479, 2015). "Herein, the non-canonical Wnt5A was upregulated in two multidrug-resistant cancer cell lines, MES-SA/Dx5 and MCF7/ADR2 cells." (PMID 25401518, 2014). "Wnt5a is classified as a non-transforming Wnt family member and plays complicated roles in oncogenesis and cancer metastasis." (PMID 24524196, 2014). "Since little is known about the non-canonical Wnt protein-related pathway in drug resistant cancer cells, we have attempted in this study to investigate the role of the non-canonical Wnt5A in drug-resistant cancer cells." (PMID 25401518, 2014). "In addition to WNT5A, WNT16 and WNT2B also produce alternative transcripts that are differentially expressed in human tissues and cancers." (PMID 24260410, 2013). "The patients with Wnt5a-positive tumors had a slightly higher median cancer-specific survival than those with negative Wnt5a expression (8.7 vs. 6.8 months); however, the difference was not statistically significant (P > 0.05)." (PMID 24156409, 2013). "In support of this hypothesis previous studies have reported the role of Wnt5a as a pro-angiogenic gene and also the importance of the Wnt signaling pathway in epithelial-mesenchymal transition (EMT) of cancer." (PMID 23947922, 2013). "The median cancer-specific survival was comparable between patients with positive versus negative expression of Wnt5a." (PMID 24156409, 2013). "Interestingly, in undifferentiated cells, genes involved in cancer/inflammatory pathways such as CXCL12, IGFBP3, IL1B, and WNT5A were down-regulated by PCB-153, whereas they were up-regulated by AhR ligands." (PMID 22262711, 2012).